BRCA1 (BRCA1 DNA repair associated)
Diseases named in the same sentence as BRCA1 in open-access papers (continued):
Sharing a sentence is not in itself a finding about the gene and the disease.
breast cancer (continued). "Our results provide evidence that deficient DNA repair may be a biomarker to identify higher-risk individuals in BRCA1 families, and provides an a priori hypothesis for further studies of BRCA1 and RAD51 SNPs in familial breast cancer risk." (PMID 21708019, 2011). "Our findings suggest that while gene fusions are present in some BRCA1-mutated breast cancers, they are infrequent and not recurrent." (PMID 22032724, 2011). "The data is from a breast cancer study (P002 BRCA1) provided by NGRL-Manchester." (PMID 21682923, 2011). "Here we depict a molecular mechanism involving BRCA1 and RHAMM that regulates apicobasal polarity and, when perturbed, may increase risk of breast cancer." (PMID 22110403, 2011). "Taken together, chromatin structure, methylation status of the gene promoter and dynamic transcription factor recruitment may work together to affect BRCA1 expression in breast cancer cells." (PMID 21668996, 2011). "Although much is known about the molecular genetics of BRCA1 in breast cancer, its association with CSC markers has not been studied in detail." (PMID 23508738, 2011). "Germ line mutations in BRCA1 and BRCA2 account for 5% to 10% of all breast cancer in women, and correspondingly in dogs, germ line mutations in the same genes, as determined by candidate gene association, have also been shown to predispose to canine mammary carcinoma." (PMID 24212780, 2011). "Some women with a strong family history of breast cancer inherit BRCA1 or BRCA2 mutations, which have a variable penetrance for breast cancer, between 40 to 66%, suggesting that additional factors contribute to cancer risk among BRCA1 and BRCA2 carriers." (PMID 21708019, 2011). "In the group of families with no ovarian cancer but at least two or more breast cancer cases with only one of them diagnosed before the age of 50 (Group C), the mutation detection rate for BRCA1 was 11% and for BRCA2 8% or 19% for both genes." (PMID 21232165, 2011). "This study suggests that treatment with an HDAC inhibitor enhances the cytotoxicity of cisplatin therapy in ovarian and breast cancer cells and that this increased sensitivity may be mediated by a BRCA1 mechanism." (PMID 21854619, 2011). "HCC1937 cells demonstrated detectable levels of BRCA1 mRNA, albeit lower than the other breast cancer cell lines examined, which is in keeping with the previous observation that tumors from germ line mutation carriers express mRNA levels lower than in sporadic tumors." (PMID 21854619, 2011). "Importantly, both proteasome inhibition and BRCA1 depletion increased the abundance of RHAMM, which is also consistent with observed RHAMM over-expression in breast cancer cell lines derived from BRCA1 mutation carriers." (PMID 22110403, 2011). "Other studies have also demonstrated an association between BRCA1 hereditary breast cancer and the presence of CD44+/CD24- cells, whereas our study points to the relationship between BRCA1 and CSC marker CD44 in unselected breast cancer patients rather than only in hereditary breast cancer patients." (PMID 23508738, 2011). "BRCA1 and BRCA2 are the most prominent breast cancer susceptibility genes." (PMID 21835029, 2011). "In a genetically engineered mouse model (GEMM) for BRCA1-associated breast cancer, AZD2281 treatment inhibited tumour growth without signs of toxicity." (PMID 22332018, 2011). "Based on this role, the frequent downregulation of BRCA1 expression seen in sporadic breast cancers could reflect the disruption of a stem cell differentiation program." (PMID 21609478, 2011). "It has been repeatedly shown, that the majority of BRCA1-mutated breast carcinomas (BC) do not express ER, while the hormonal receptor pattern in BRCA2-associated BC is similar to sporadic cases." (PMID 21819606, 2011).
breast cancer (continued). "It is also possible that no breast cancer that develops in a BRCA1 mutation carrier is really 'incidental' or sporadic, even if LOH of wt BRCA1 does not exist." (PMID 20149218, 2010). "However, approximately 10 to 36% of breast cancers that occur in BRCA1 carriers are estrogen receptor-positive (ER+)." (PMID 21080930, 2010). "In one study, short-term breast fibroblast cell-lines were established from nine individuals with a BRCA1 germ-line mutation, and five healthy control individuals with no personal or family history of breast cancer." (PMID 20174566, 2010). "It is possible that no breast cancer that develops in a BRCA1 mutation carrier is really "incidental" or sporadic even if one functioning wt BRCA1 allele is retained and expressed." (PMID 21080930, 2010). "The obtained data indicated that antimitotic effect of D-glucuronyl C5-epimerase in human breast cancer cells in vitro probably is realized mainly via the activation of tumour suppressor genes р53, BRCA1, SYK and E2F1 and change of a balance of pro- and anti-apoptotic factors BCL2, NFKB1 and TNF." (PMID 20723247, 2010). "Many of the new therapies being evaluated in BRCA1 breast cancers, such as poly(ADP-ribose) polymerase (PARP) inhibitors and cisplatin, are designed to take advantage of the defect in homologous recombination that BRCA1 deficiency causes in these cancers." (PMID 21080930, 2010). "Besides the tumor suppressor BRCA1, we identified three more candidate genes whose expression was demonstrated to be of importance for the proliferation of the breast cancer cell line MDA-MB-231." (PMID 20051122, 2010). "Our results provide evidence for the existence of familial factors, such as variants in genes other than BRCA1 and BRCA2, which contribute to the increased risks for breast, prostate, lung and/or brain cancers in relatives of women with very early-onset breast cancer." (PMID 20877337, 2010). "Whilst the risk of breast and ovarian cancer in the general population is 10%-13% and 1.7%, respectively, studies indicate that a woman with mutations in either BRCA1 or BRCA2 carries a lifetime breast cancer risk of 80% and 20%-60% for developing breast cancer and ovarian cancer respectively." (PMID 20961453, 2010). "Additionally, BRCA1 and BRCA2 mutational carriers, who are also smokers, are at an increased risk of getting breast cancer." (PMID 20591176, 2010). "Those women found to carry BRCA1/2 mutations are at markedly increased probability of developing hereditary breast and ovarian cancer (HBOC), with their lifetime risk of breast cancer between 45% and 88%, and their risk of ovarian cancer ranging from 11% to 65%." (PMID 20687957, 2010). "Age at diagnosis was not significantly different between first invasive ER+ BRCA1 breast cancers with and without loss of wt BRCA1 (mean age 45.2 years vs 50.1 years, respectively; P = 0.51)." (PMID 21080930, 2010). "The expression of ID4 and BRCA1/ER inversely correlated in sporadic breast cancers." (PMID 21293053, 2010). "Although of controversial value as an immunohistochemical biomarker, the relationship between BRCA1 status and basal-like breast cancer could potentially lead to great progress in the field." (PMID 24281106, 2010). "Besides ER status, other documented genetic variables important in breast cancer research include progesterone receptor status (PR), the HER2/neu receptor, and the BRCA1 and BRCA2 mutation status." (PMID 20964848, 2010). "We conducted a small qualitative study that investigated women who had developed breast cancer under the age of 45 and who had an inconclusive BRCA1/2 genetic diagnostic test (where no mutations or unclassified variants were identified)." (PMID 20180951, 2010).
breast cancer (continued). "The majority of breast cancers that occur in BRCA1 mutation carriers (BRCA1 carriers) are estrogen receptor-negative (ER-)." (PMID 21080930, 2010). "Several reports suggested that women with germline mutations in BRCA1 are more likely to die from their disease than are women with sporadic breast cancer, whereas BRCA2 mutation carriers and non-mutation carriers seem to share a similar prognosis." (PMID 20219108, 2010). "We successfully genotyped 24 SNPs in a cohort of up to 4,724 BRCA1 and 2,693 BRCA2 female mutation carriers from 15 study groups and assessed whether these variants were associated with risk of breast cancer in BRCA1 and BRCA2 mutation carriers." (PMID 21114847, 2010). "Although the E3 ligase that targets BRCA1 for proteolysis remains unknown, the enhanced degradation of BRCA1 by a deregulated E3 ligase could be one of the mechanisms by which BRCA1 levels are reduced in sporadic breast cancer." (PMID 21217819, 2010). "The aim of this study was to evaluate the absence of LVI as a putative biomarker in BRCA1 germline mutation related breast cancer." (PMID 20398395, 2010). "A similar idea seems to have guided an investigation of the CHEK2 gene in breast cancer that was carried out using non-carriers of BRCA1 or BRCA2 mutations." (PMID 21187953, 2010). "Although many women with BRCA mutations have a high probability of developing breast cancer, 15% of BRCA1-positive women and 20% of BRCA2-positive women will never develop breast cancer." (PMID 21037853, 2010). "Because BRCA1 is the most frequently mutated gene in hereditary breast cancers, the relationship between AKT1 and BRCA1 could constitute the missing molecular link between sporadic and familial breast cancers." (PMID 21321378, 2010). "Although prophylactic mastectomy is the most effective intervention for BRCA1 and BRCA2 carriers, reducing the risk of developing breast cancer by 90%, mastectomy is a highly invasive procedure with adverse physical and potentially devastating psychological effects." (PMID 21037853, 2010). "In the clinic, the available evidence is not sufficient to conclude that BRCA1/2-associated breast cancer is differentially sensitive to specific conventional chemotherapeutic agents." (PMID 20877358, 2010). "Although rare, somatic PTEN mutations have previously been reported in breast cancer, but they were seen mainly in the basal-like tumors class characterized by a loss of expression of PTEN and more specifically in tumors from patients with BRCA1 mutations." (PMID 20712882, 2010). "This subtype of breast cancer is more common among BRCA1 gene mutation carriers, however, known BRCA1 and BRCA2 mutations do not seem to explain the triple negative cancer in Indian women." (PMID 20459777, 2010). "Additionally, because the PI3K/AKT chemical inhibitor, LY294002, has been described to control BRCA1 activation in breast cancer cells, this inhibitor was also used in parallel to MG132." (PMID 21203397, 2010). "Mutations in BRCA1 and BRCA2 are found in a proportion of multiple case breast cancer families." (PMID 20807450, 2010). "Moreover, reconstitution of BRCA1 in the BRCA1 mutant HCC1937 breast cancer line or BRCA1-null UWB1.289 ovarian cancer cell line resulted in a reduced sensitivity to the DNA damage chemotherapeutic agents or ionizing radiation." (PMID 21217819, 2010). "Despite the strong contribution of BRCA1 to hereditary breast and ovarian cancer, mutations in BRCA1 do not account for all cases of inherited breast cancer, implicating the existence of a second major susceptibility gene." (PMID 21037853, 2010).
breast cancer (continued). "We have previously shown that the pathologic features of ER+ invasive breast cancers that arise in BRCA1 carriers are significantly different than age-matched sporadic ER+ breast cancers in non-mutation carriers." (PMID 21080930, 2010). "BRCA1 and BRCA2 genes have been identified that confer a high degree of breast cancer risk." (PMID 20579331, 2010). "9-22% of sporadic breast cancers have been described to show promoter hypermethylation of BRCA1 or loss of heterozygosity at the BRCA1 locus and these tumors are largely ER and PR negative, of ductal and medullary type, and high grade." (PMID 20398395, 2010). "Most breast cancers that occur in women with germline BRCA1 mutations are estrogen receptor-negative (ER-) and also typically lack expression of progesterone receptor (PR) and HER2 overexpression." (PMID 20149218, 2010). "Mutations in BRCA1 and BRCA2 confer high risks of breast cancer and ovarian cancer." (PMID 20482762, 2010). "Collectively, these results indicate that BRCA1 is methylated in breast cancer cell lines." (PMID 20614009, 2010). "Nonetheless, taken together the results of these two studies raise the possibility that not all BRCA1-associated breast cancers exhibit complete loss of BRCA1 function." (PMID 20149218, 2010). "The Breast Cancer Information Core Database (BIC database), a public archive of BRCA mutations, has collected the whole series of BRCA1 and BRCA2 coding variants, amounting up until now to about 1,300 deleterious mutations in the two genes, identified from various population studies." (PMID 24281179, 2010). "First-degree relatives of women with very early-onset breast cancer are at increased risk of cancers not explained by BRCA1 and BRCA2 mutations." (PMID 20877337, 2010). "Studies of sporadic breast cancers have not found reproducible associations between BRCA1 promoter methylation and tumor phenotype." (PMID 21080930, 2010). "It has been previously reported that ER+ breast cancers are more likely to develop in BRCA1 carriers as they age, suggesting that some of these may be incidental breast cancers occurring in BRCA1 carriers." (PMID 21080930, 2010). "Other studies have proposed wt BRCA1 is essential for differentiation of mammary stem cells to ER+ luminal cells and that loss of wt BRCA1 causes an expansion of ER-negative mammary stem cells, offering a mechanism for the common ER-negativity of BRCA1 breast cancers." (PMID 21080930, 2010). "For example, mutating the BRCA1 or BRCA2 genes confers a hereditary predisposition to breast cancer in the absence of exposure to exogenous genotoxic agents." (PMID 21321378, 2010). "The breast cancer predisposition genes BRCA1 and BRCA2 have been reported to increase the risk of PrCa by three-fold and seven-fold, respectively, in male mutation carriers ascertained through a family history of breast cancer." (PMID 20736950, 2010). "BRCA1 methylation and abrogation of BRCA1 mRNA have been reported in sporadic breast cancers." (PMID 20209131, 2010). "In sporadic breast cancer, absent or reduced BRCA1 expression was associated with high tumor grade, advanced lymph node stage, larger size, vascular invasion, negative estrogen receptor, negative progesterone receptor and poor outcome." (PMID 20209131, 2010). "To gain insight into the specific effects of BRCA1 or BRCA2 loss on genomic instability, we used aCGH profiles of genetically defined mouse models for BRCA1- and BRCA2-associated breast cancer as biological data filters to mine the human breast cancer genome." (PMID 20735817, 2010). "BRCA1 and BRCA2 genes mutations are responsible for a significant proportion of breast cancer." (PMID 20579331, 2010). "A series of preclinical and clinical studies have indicated that most triple negative/basal-like breast cancers have dysfunctional BRCA1 or loss of BRCA1 expression." (PMID 20959018, 2010).
breast cancer (continued). "Our data suggest that sporadic breast cancer patients with low levels of BRCA1 mRNA expression may obtain the greatest benefit from anthracycline-based therapy." (PMID 20209131, 2010). "The higher breast cancer FRR for younger relatives of ER-negative and PR-negative disease may be due to enrichment in BRCA1 as tumours from BRCA1 mutation carrier status very often arise in younger individuals and are ER and PR negative." (PMID 20146796, 2010). "Furthermore, ER+ BRCA1 breast cancers appear to be pathologically 'intermediate' between ER- BRCA1 cancers and ER+ sporadic cancers, thus comprising a unique group." (PMID 20149218, 2010). "To investigate the impact of BRCA1 and BRCA2 deficiency on chromosomal instability in breast epithelial cells, we performed aCGH on mammary tumors derived from our genetically engineered mouse (GEM) models for BRCA1- and BRCA2-associated breast cancer." (PMID 20735817, 2010). "Given that BRCA1 -related breast cancers generally have the same phenotypic expression profiles as BRCA-negative basal breast cancers, it has been hypothesized that sporadic TRN breast cancers may have a DNA repair deficit similar to that in BRCA-mutant cases." (PMID 21050422, 2010). "An intriguing thought is the possibility that these genes may act as potential modifiers of BRCA1 and/or BRCA2 associated breast cancer risk." (PMID 20174566, 2010). "In summary, the obtained results showed that D-glucuronyl C5-epimerase significantly suppress proliferative activity of breast cancer cells in vitro through the activation of tumour suppressor genes р53, BRCA1, SYK and E2F1 and change of a balance of pro- and apoptotic factors BCL2, NFKB1 and TNF." (PMID 20723247, 2010). "The BRCA1/2 mutation is not yet a targeted tool to determine a population of breast cancer at high risk of local relapse." (PMID 20074364, 2010). "A fraction of sporadic breast cancers has low BRCA1 expression." (PMID 20209131, 2010). "To distinguish between those ER- BRCA1-associated breast cancers that did or did not have loss of the wt BRCA1 allele, however, we found the combination of CK5/6 and CK14 most useful." (PMID 21080930, 2010). "In contrast to this, only 2% of non-familial patients had pathologic germline mutations in BRCA1 and 2 genes in a group of English patients who were diagnosed with breast cancer at the age of 30 years or younger." (PMID 20579331, 2010). "These clinical attributes contribute to the “basal-like” phenotype of BRCA1 breast carcinomas and may influence tumor behavior and aggressiveness." (PMID 21037853, 2010). "BRCA1 related breast carcinomas have a distinct histopathological phenotype." (PMID 20398395, 2010). "Families with two or more breast cancers under the age of 50 years, or with three cases of breast cancer at any age, and who tested negative for a BRCA1 or BRCA2 mutation were identified." (PMID 19088722, 2009). "In 2003 our group has demonstrated a differential chemosensitivity profile in vitro of BRCA1-mutated HCC1937 breast cancer cells with bi-allelic loss as compared to the derivative clone HCC1937WT, where the BRCA1 expression has been reconstituted by transfection of a BRCA1 full length cDNA." (PMID 19825178, 2009). "An Sp1 boundary phenomenon has been reported in the BRCA1 promoter of breast cancer cells." (PMID 19912643, 2009).